NEAT1 (nuclear paraspeckle assembly transcript 1)
Diseases named in the same sentence as NEAT1 in open-access papers (continued):
Sharing a sentence is not in itself a finding about the gene and the disease.
tumor (continued). "Research suggests that M2-derived EVs containing NEAT1 have a tumor-promoting effect on OC through the miR-101–3p/ZEB1/PD-L1 axis." (PMID 38903506, 2024). "In certain cancers, NEAT1 recruits miRNAs and prevents them from inhibiting downstream gene expression, ultimately leading to enhanced tumor growth and invasion." (PMID 38646788, 2024). "An experiment was conducted utilizing shNEAT1 in a tumor formation model to analyze the effect of NEAT1 on the regulation of TMZ chemosensitivity in a tumor formation animal model (n = 6)." (PMID 39453684, 2024). "The NEAT1 (a long noncoding RNA) participates in invasion, chemoresistance in EC cells, and remodeling tumor microenvironment by induced miR-361 suppression, which activates STAT3." (PMID 39188680, 2024). "In a xenograft tumor mouse model, the PTX group or NEAT1 knockdown inhibited tumor growth, while combined sh-NEAT1 with PTX caused a more significant inhibition of tumor growth." (PMID 38356722, 2024). "LncRNA NEAT1 is a novel lncRNA discovered in recent years, and its normal expression is related closely to apoptosis and cell cycle of tumor cells." (PMID 38709402, 2024). "Previous studies showed that silencing NEAT1 inhibits the invasion of OC cells in vitro and attenuates tumor growth in vivo." (PMID 39149564, 2024). "LncRNA NEAT1 is upregulated in EC tissues, and its abundance is correlated with higher tumor proliferation capacity." (PMID 39188680, 2024). "They indicated that NEAT1 expression levels were directly correlated with tumor bulk, suggesting that this lncRNA facilitates cell proliferation by activating the Akt signaling pathway." (PMID 39246994, 2024). "EC cell exosomes transfer proteins in CAFs as NEAT1, which is able to modulate the activity of several mi-RNA related to tumor growth in a xenograft model of HEC-1A EC cells." (PMID 38731868, 2024). "NEAT1 (nuclear paraspeckle assembly transcript 1), a lncRNA distinguished by its nuclear enrichment, has emerged as a focal point of interest due to its multifaceted influence within the tumor microenvironment." (PMID 39286016, 2024). "Inhibition of NEAT1 significantly inhibits tumor growth in mice, but PGK1 can reverse this effect, indicating that NEAT1 overexpression promotes tumor development." (PMID 38967893, 2024). "We utilized RNA-seq data from the TCGA database to analyze the expression of NEAT1 among various tumor tissues." (PMID 38356722, 2024). "NEAT1 promotes tumor progression through two mechanisms: miRNA sponge or interaction with scaffold protein such as enhancer of zeste homolog 2 (EZH2)." (PMID 38646788, 2024). "By activating PRC2, NEAT1 acts as an oncogene and promotes tumor development and progression in coordination with EZH2." (PMID 38646788, 2024). "There was evidence that N6 methyl adenosine (m6A) modification mediated tumor progression of RCC by regulating lncRNA NEAT1." (PMID 36969848, 2023). "The expression level of onco-lncRNAs, including PCAT19, MALAT1, and NEAT1, and the tumor suppressor lncRNA, CASC2, was increased and decreased, respectively, in PCa patients compared to the healthy group (P < 0.05)." (PMID 37251950, 2023). "Metascape analysis revealed that the ATP metabolic process and response to oxygen levels pathway were enriched in NEAT1+ tumor cells, where oxidative phosphorylation (OXPHOS)-related genes, COX1, COX2, COX3, ND1, ND2, ND4, and ATP6, were clustered." (PMID 37430270, 2023). "Specifically, hypoxia-induced ALKBH5 removed m6A modification from the LncRNA NEAT1, enhancing its transcript stabilization and promoting NEAT1-mediated paraspeckle assembly, ultimately generating an immunosuppressive tumor microenvironment." (PMID 37365581, 2023). "Apart from its role as a miRNA sponge, NEAT1 also plays a pivotal role in ferroptosis, a unique form of cell death driven by iron-dependent lipid peroxidation, crucial for tumor development and drug resistance." (PMID 37759495, 2023).
tumor (continued). "miR‐204 as a tumor suppressor was found to reduce the stimulatory effect of NEAT1 on cell proliferation." (PMID 37310654, 2023). "One of the lncRNAs, nuclear paraspeckle assembly transcript 1 (NEAT1), has received considerable attention due to its validated associations with tumour migration and progression." (PMID 37343193, 2023). "Another limitation is its sample size of clinical tissues and single data source when evaluating the expression levels of NEAT1 in tumor and non-tumor tissues." (PMID 37986114, 2023). "LncRNA NEAT1 can act as a ceRNA for miR‐34a‐5p and is highly expressed in colorectal cancer tumour tissues and cells." (PMID 37837401, 2023). "Compared with these control groups, the group with NEAT1-overexpression exhibited markedly enhanced tumor growth, while the group with NEAT1-knockdown showed obviously decreased tumor volumes, which was observed in both SKOV-3 xenograft and A2780 xenograft." (PMID 37986114, 2023). "Nevertheless, another study revealed that NEAT1 expression was significantly higher in RCC cell lines than that in non-tumor cells, with the highest expression in 786-O and ACHN cell lines." (PMID 36969848, 2023). "NEAT1 can bind with multiple downstream miRNAs (sncRNA with approximately 22 nts) and regulate tumor growth and progression." (PMID 37310654, 2023). "RELB, NFKB1, BCL3, and FOXO3, found in NEAT1+ tumor cells, were closely related to the CSCs phenotype." (PMID 37430270, 2023). "Lastly, a group of cells, emerged as specifically expressing non‐coding RNAs with a tumor‐associated role, such as MEG3, NEAT1, and FTX (Fig EV5C and D)." (PMID 38037472, 2023). "Specifically, NEAT1+ tumor cells with the CSCs phenotype were observed in the initial portion, followed by two separate trajectory branches: apoptotic CSCs FSTL1+ tumor cells and EMT tendency and immune-associated S100A4+ tumor cells." (PMID 37430270, 2023). "Bioinformatical analysis and luciferase assay were used to demonstrate that the tumor suppressor miR-23a-3p can be downregulated through sponging by NEAT1." (PMID 37175800, 2023). "We created a 288 nt fragment of NEAT1–Region 2 for wild-type (WT) and mutated (MUT) sequence, the latter containing two SNVs observed in patient tumours." (PMID 37291246, 2023). "NEAT1 knockdown cells produced smaller tumors, demonstrating that NEAT1 promotes tumor growth in vivo." (PMID 37946156, 2023). "LncRNA NEAT1 participates in tumor differentiation, metastasis and TNM staging of CRC via NEAT1/miR-495-3p/CDK6 axis." (PMID 38309281, 2023). "NEAT1 is expressed at lower levels in tumor samples with high levels of cytotoxic CD8+ infiltration." (PMID 37161350, 2023). "Nuclear-enriched-abundant transcript 1 (NEAT1) affects BLCA tumor growth by participating in cell proliferation and migration through its interaction with miR-101 and miR-410." (PMID 37373000, 2023). "Many studies have identified NEAT1’s aberrant expression and prognostic relevance in a variety of tumors; the majority of them define NEAT1 as an oncogene that is overexpressed in tumors compared with normal tissues and it commonly boosts tumor cell growth." (PMID 37343193, 2023). "Altogether, these findings suggest a model where tumour SNVs alter the protein interactome of NEAT1, leading to both gains and losses of protein partners." (PMID 37291246, 2023). "In the xenograft mouse model, more NEAT1 expression resulted in faster in vivo tumor growth, more blood vessel formation in tumor tissues, as well as higher expression levels of angiogenesis-related molecules and CD31." (PMID 37986114, 2023).
tumor (continued). "Among them, the expression of NEAT1 was significantly higher than that of other lncRNAs, and it has been reported to be involved in tumor development, progression and treatment." (PMID 35338333, 2022). "In conclusion, these results indicated that knockdown of NEAT1 inhibits tumor growth and inflammation-related gene expression in-vivo." (PMID 36213831, 2022). "At present, lncRNA NEAT1 expression changes have been found in a variety of human tumors, and it is related to tumor metastasis, occurrence, and development." (PMID 36185217, 2022). "In conclusion, these results indicated that NEAT1 exerted its tumor-promotive functions on PCa by the miRNA-766-5p/E2F3 axis." (PMID 35237319, 2022). "To further confirm the effect of NEAT1 on tumour growth, we generated an orthotopic BC model in vivo." (PMID 36434587, 2022). "High expression of NEAT1 is correlated with clinicopathological significance of CRC including the tumor size, distant metastasis, decreased overall survival, and disease-free survival rate." (PMID 35676702, 2022). "NEAT1 silencing blocked cell proliferation, metastasis, and facilitated apoptosis in vitro and impeded xenograft tumor growth in vivo." (PMID 35635748, 2022). "Expression of another lncRNA with oncogenic properties, nuclear-enriched abundant transcript 1 (NEAT1), was significantly increased in PCa tumour versus benign tissues and elevated in DTX-resistant versus-responsive tumour samples." (PMID 35159022, 2022). "HB-derived exosomal lncRNA NEAT1 induced BMSCs differentiation into tumor-supporting myofibroblasts via modulating miR-132/MMP9 axis, which provided a new target for HB treatment." (PMID 35300348, 2022). "Long noncoding RNA (lncRNA) nuclear paraspeckle assembly transcript 1 (NEAT1) has been reported to be involved in the regulation of cell cycle, proliferation, apoptosis, and migration of tumor cells." (PMID 35338333, 2022). "Among lncRNAs relevantly expressed in malignant PCs, we have recently focused on the nuclear paraspeckle assembly transcript 1 (NEAT1) demonstrating that its targeting impairs the DNA repair machinery and triggers anti-tumor activity in MM." (PMID 36367609, 2022). "Conversely, the interaction between miR-155 and the lncRNA Nuclear-Enriched Abundant Transcript 1 (NEAT1) can interfere with tumor progression in mice, thus enhancing CD8 T cell cytolysis." (PMID 36230554, 2022). "Arguably, the expression levels and the ratio of NEAT1 isoforms in tumours are regulated by a complex interplay of oncogenes and tumour suppressors that steer the transcription, 3′ end formation, localisation and stability of NEAT1 isoforms." (PMID 35457249, 2022). "In addition, PGK1 could reverse the inhibition of tumor growth caused by NEAT1 knockdown." (PMID 35123484, 2022). "Mature miR-612 is a tumor-suppressive gene generated by alternative splicing, and the balance between the two NEAT1 transcripts and miR-612 can be regulated by polypyrimidine tract binding protein 3 (PTBP3)." (PMID 36011001, 2022). "Mechanistically, NEAT1 acts as a sponge to absorb miRNA, thereby promoting the growth of tumor cells." (PMID 35338333, 2022). "Downregulated NEAT1 impaired the viability of CRC cells whereas miR-193a-3p inhibition increased tumor cell proliferation and migration, and reduced CRC apoptosis by targeting Kirsten rat sarcoma viral oncogene homology (KRAS) expression." (PMID 35676702, 2022). "From this, we concluded that RBM10 regulated AS of Neat1, and the tumor-promoting effect of Neat1 was mainly attributed to Neat1_2." (PMID 36335386, 2022). "The observed effects of NEAT1 on ferroptosis suggest that the expression level of NEAT1 should modulate the anti-tumor activity of erastin and RSL3." (PMID 35338333, 2022). "More interestingly, we found that the level of NEAT1 in PCa patients with tumor stage III + IV was higher than that of stage I + II." (PMID 35237319, 2022).
tumor (continued). "We analyzed the associations among nine lncRNAs (NEAT1, XIST, NORAD, MALAT1, MIR29B2CHG, LINC00943, AC005332.4, AC092718.4, and LINC01146), risk score, tumor purity, and immune cell infiltration." (PMID 35756601, 2022). "NEAT1 was shown to have relevance for modulating replication, the stress response, tumour formation or human embryonic stem cell (hESC) differentiation." (PMID 36344775, 2022). "Based on this, we conducted a number of experiments to show that HB-derived exosomal lncRNA NEAT1 induced BMSCs to differentiate into tumor-supporting myofibroblasts by regulating the miR-132/MMP9 axis." (PMID 35300348, 2022). "H&E staining and IHC experiments showed that the malignant degree of tumor tissue decreased, and the level of Ki-67 decreased in NEAT1 knockdown tumor tissue." (PMID 36213831, 2022). "In the present study, a novel mechanism of action of NEAT1 was demonstrated to promote tumour development of BC by modulating the miR-101/VEGF-C pathway, providing novel insight into therapeutic application of lncRNAs in BC." (PMID 36434587, 2022). "NEAT1 plays a role in chemo-resistance, tumor growth, and metastasis, according to several lines of evidence." (PMID 35676702, 2022). "We also found high expression of NEAT1 mRNA significantly correlated with distant metastasis (p < 0.01), lymph node metastasis (P=0.0001), and tumor grade (P=0.011)." (PMID 36262350, 2022). "Elevated levels of NEAT1 isoforms generally promote tumour development in mouse models and function as a prognostic marker for patient survival." (PMID 35457249, 2022). "Overexpression of NEAT1 promoted tumor growth, while PKM2 knockdown reversed the oncogenic effect of NEAT1." (PMID 36185217, 2022). "LncRNA nuclear enrichment enriched transcript 1 (Lnc NEAT1) has been found to be abnormally upregulated in various human cancer types with the ability to promote tumor growth." (PMID 35850692, 2022). "Then RNA was extracted from tumor tissue, and qRT-PCR showed that the expression of NEAT1, IL-34, VEGFA, SPINK1, S100A14, and P4HA2 was downregulated and the expression of CCNE2 was upregulated in NEAT1 knockdown tumor tissue." (PMID 36213831, 2022). "lncRNA NEAT1 induces tumor cell proliferation and induces M2 TAM polarization via molecular sponging of miR-214 and regulates the expression of B7-H3 (immune checkpoint regulator)." (PMID 33522932, 2021). "They found that NEAT1 overexpression inhibited tumor proliferation and promoted apoptosis via regulating the miR-92b/DKK axis." (PMID 34322395, 2021). "The primary tumour weight and volume data indicated that NEAT1 KD significantly suppressed tumour growth." (PMID 33546665, 2021). "NEAT1 expression can be up-regulated in HCC tissues, and NEAT1 can promote the expression of Uridine-Cytidine Kinase 2 (UCK2) by competitively binding to the tumor suppressor miR-199a-3p, so as to maintain the growth of HCC cells." (PMID 34758879, 2021). "HCT116 or RKO cells infected were injected with NEAT1 knockdown lentivirus to establish the subcutaneously implanted tumor model in mice." (PMID 34395239, 2021). "The tumor weight after anlotinib treatment was improved from approximately 40% to near 80% after combined therapy with NEAT1 siRNA3." (PMID 33982669, 2021). "Mice injected with sh-NEAT1-transfected U2OS cells had significantly smaller primary tumour volumes and weights than mice injected with sh-NC U2OS cells (p < 0.05)." (PMID 33546665, 2021). "Knockdown of NEAT1 expression results in a reduction in xenograft tumor growth as well as increases sensitivity to cisplatin." (PMID 34680193, 2021). "Statistical analysis revealed that high NEAT1 expression levels were correlated with advanced T stage and big tumor size in GC patients." (PMID 34552925, 2021). "Silencing NEAT1 or PDT treatment alone significantly decreased the volume and weight of the tumor, and NEAT1 silencing combined with PDT treatment decreased the most." (PMID 34395239, 2021).
tumor (continued). "NEAT1’s abnormally high expression was also instrumental in influencing tumour size, lymph node metastases and overall survival in a cohort of 40 BC patients." (PMID 33807045, 2021). "Cell division cycle 5-like protein (CDC5L) is essential for mitotic progression, and its target gene, AGRN, seems to be modulated by NEAT1, yielding this whole pathway critical for tumor growth." (PMID 33917553, 2021). "As one newly discovered lncRNA, NEAT1 also participates in the occurrence and development of various tumours and regulates tumour cell invasion and metastasis." (PMID 33546665, 2021). "TU212 cells were implanted into BALB/c mice by subcutaneous injection to investigated NEAT1 silence on the growth of tumor." (PMID 34837887, 2021). "In this review, we discuss the roles of NEAT1 in the progression of different types of tumors by describing a universal regulatory pattern of NEAT1 in tumor-related gene expression." (PMID 34512157, 2021). "In the study of this subject, we screened and analyzed multiple databases and found the LncRNA NEAT1 with obvious differential expression in RCC tumor tissues compared to normal tissues." (PMID 34957107, 2021). "Mechanistic studies confirmed that MRP-7 is a direct target of tumor suppressor miR-98, and NEAT1 sponges miR-98 to increase MRP-7 levels in EC cells." (PMID 34950596, 2021). "Within a subcutaneously implanted tumor model in mice, silencing NEAT1 enhanced the inhibitory roles of PDT in tumor growth." (PMID 34395239, 2021). "NEAT1 and MALAT1 are well characterized lncRNAs and have been implicated in tumor progression, including GBM." (PMID 33466745, 2021). "CRISPR/Cas13b-METTL3 targeting LncRNA NEAT1 m6A methylation activates LncRNA NEAT1 expression and suggested its potent tumor-suppressive function." (PMID 34957107, 2021). "Increasing reports have indicated that lncRNA NEAT1 shows tumor-promoting functions in a variety of malignancies, including EC." (PMID 34950596, 2021). "These in vivo findings indicate that the silencing of NEAT1 enhances the suppressive roles of PDT treatment in tumor growth in the subcutaneously implanted tumor model in mice." (PMID 34395239, 2021). "The effect of NEAT1 siRNA3 combined with anlotinib on tumor growth was investigated in a mouse xenograft model." (PMID 33982669, 2021). "Within the subcutaneously implanted tumor model, NEAT1 silencing enhanced PDT-induced suppression on tumor growth." (PMID 34395239, 2021). "Within the subcutaneously implanted tumor model, NEAT1 silencing promoted the suppressive roles of PDT in tumor growth." (PMID 34395239, 2021). "High NEAT1 expression correlates with larger tumor size, higher WHO grade, prognosis, and recurrence." (PMID 33466745, 2021). "Analogously, in contrast to miR-128-3p downregulation alone, co-downregulation of NEAT1 and miR-128-3p in xenograft cells resulted in larger tumor volume." (PMID 34263426, 2021). "Nuclear paraspeckle assembly transcript 1 (NEAT1) is one lncRNA that has been discovered in recent years and is implicated in the progression of various tumours." (PMID 33546665, 2021). "NEAT1 lncRNA was highly expressed in the peripheral blood mononuclear cells (PBMCs) and tumor tissues of patients with HCC." (PMID 32083005, 2020). "Alternatively, we suggest that traditional chemotherapy be combined with drugs that target tumor stem cells to treat CRC patients with high levels of NEAT1." (PMID 33168814, 2020). "The effects of NEAT1 knockdown on the tumor growth in vivo were detected by in vivo tumor formation assay." (PMID 33281873, 2020). "Furtherly we analyzed the expression of NEAT1 in tumor tissues with different clinical characteristics." (PMID 33680941, 2020).